SDHB (succinate dehydrogenase complex iron sulfur subunit B)
Description:
Iron-sulfur protein (IP) subunit of the succinate dehydrogenase complex (mitochondrial respiratory chain complex II), responsible for transferring electrons from succinate to ubiquinone (coenzyme Q). SDH also oxidizes malate to the non-canonical enol form of oxaloacetate, enol-oxaloacetate (By similarity). Enol-oxaloacetate, which is a potent inhibitor of the succinate dehydrogenase activity, is further isomerized into keto-oxaloacetate (By similarity).
Synonyms: Ip; SDH; SDH1; CWS2; MC2DN4; PGL4; PPGL4; SDH2; SDHIP
Tractability: Small molecule: a structure with a bound ligand is known; a high-quality ligand is known. Antibody: UniProt places it where antibodies can reach, with high confidence; its Gene Ontology location is reachable by antibodies, with high confidence. PROTAC: ubiquitination databases record sites on it; its protein half-life has been measured; a small molecule that binds it is known.
Target class: Enzyme; Oxidoreductase
Gene: Protein-coding gene on chromosome 1 (17,018,664 to 17,054,151, reverse strand). Ensembl gene ENSG00000117118.
Subcellular location: Mitochondrion inner membrane
Subcellular location (Human Protein Atlas): Mitochondria; Nucleoplasm; Plasma membrane
Pathways (Reactome):
Metabolism: Citric acid cycle (TCA cycle); Maturation of TCA enzymes and regulation of TCA cycle; Respiratory electron transport
Gene Ontology:
Molecular function: protein binding; succinate dehydrogenase (quinone) activity; 2 iron, 2 sulfur cluster binding; 3 iron, 4 sulfur cluster binding; 4 iron, 4 sulfur cluster binding; ubiquinone binding; electron transfer activity; iron-sulfur cluster binding; oxidoreductase activity
Biological process: aerobic respiration; mitochondrial electron transport, succinate to ubiquinone; proton motive force-driven mitochondrial ATP synthesis; respiratory electron transport chain; tricarboxylic acid cycle; cellular respiration; succinate metabolic process
Cellular component: mitochondrial inner membrane; mitochondrion; respiratory chain complex II (succinate dehydrogenase); mitochondrial matrix; mitochondrial membrane
Genetic constraint (gnomAD): Loss-of-function variants: 15 observed, 31.15 expected, observed/expected ratio (o/e) 0.48, 90% interval 0.32 to 0.74. The upper end of that interval is the gene's LOEUF score, 0.74, which puts it in group 3 of 6, group 1 being the genes least tolerant of losing a copy. Missense variants: 263 observed, 283.08 expected, observed/expected ratio (o/e) 0.93, 90% interval 0.84 to 1.03. Synonymous variants: 91 observed, 96.32 expected, observed/expected ratio (o/e) 0.94, 90% interval 0.8 to 1.12.
Gene-disease validity (ClinGen):
ClinGen rates the evidence that SDHB causes each of these diseases.
hereditary pheochromocytoma-paraganglioma (autosomal dominant): Definitive. Neoplasm predisposition characterized by an increased risk of paragangliomas (tumors that arise from neuroendocrine tissues distributed along the paravertebral axis from the base of the skull to the pelvis) and pheochromocytomas (paragangliomas that are confined to the adrenal medulla).
mitochondrial disease (autosomal recessive): Definitive.
Homologues: Orthologues: chimpanzee SDHB (100% identical), macaque SDHB (98% identical), dog SDHB (95% identical), rabbit SDHB (95% identical), guinea pig SDHB (94% identical), mouse Sdhb (92% identical), rat Sdhb (91% identical), pig SDHB (89% identical), tropical clawed frog sdhb (88% identical), Drosophila melanogaster SdhB (68% identical), Drosophila melanogaster SdhBL (65% identical), Caenorhabditis elegans sdhb-1 (62% identical), and 2 more.
Diseases named in the same sentence as SDHB in open-access papers:
SDHB is named in the same sentence as 224 diseases in open-access papers, as found by Europe PMC text mining. Sharing a sentence is not in itself a finding about the gene and the disease. The quoted sentences say what the papers report.
paraganglioma (199 papers, 2005 to 2026). A benign or malignant neoplasm arising from paraganglia located along the sympathetic or parasympathetic nerves. "Germline variants in the gene encoding succinate dehydrogenase subunit B (SDHB) occur in around 10% of all patients with pheochromocytomas and paragangliomas (PPGLs)." (PMID 41697738, 2026). "Pheochromocytoma and paraganglioma with a succinate dehydrogenase B subunit (SDHB) pathogenic variant are associated with a significant chance for metastasis." (PMID 42249664, 2026). "For succinate dehydrogenase (SDH)-related paraganglioma, especially those with SDHB mutations, ADC values on MRI can serve as a useful biomarker." (PMID 39794659, 2025). "SDHB mutations were documented in five of the nine phaeochromocytoma and paraganglioma patients, and patient with an insulinoma had multiple endocrine neoplasia type 1 (MEN1)." (PMID 40272497, 2025). "These analyses were performed to definitively exclude SDHB deficiency as a contributing factor in the pathogenesis of pheochromocytoma and paraganglioma in this patient with CSS." (PMID 40242210, 2025). "The loss of SDHB function has been linked to increased malignant potential and metastasis in tumors such as pheochromocytoma and paraganglioma." (PMID 41333221, 2025). "Beyond its prognostic value, SDHB deficiency has been shown to be a key driver in the development of specific tumor types, including pheochromocytomas and paragangliomas." (PMID 40724918, 2025). "Despite the absence of pathogenic variants in the SDHx genes, we aimed to further confirm SDHB expression in the pheochromocytoma and paraganglioma from the patient using RT-qPCR and Western blot analysis." (PMID 40242210, 2025). "Lately, our lab has built on these data to make a new disease model: the SDHB Arg244His mutation was introduced into the worm, which is a clinically relevant germline mutation, corresponding to Arg230His causing human paraganglioma." (PMID 39857410, 2025). "As expected, SDHB mRNA levels were reduced in a paraganglioma sample from a patient harboring the germline variant c.201-2A > G in SDHB, located near the canonical splice site and classified as likely pathogenic." (PMID 40242210, 2025). "Our report underscores the diversity in the presentation of patients with SDHB-mutated paraganglioma and the feasibility of managing it with a minimally invasive surgical approach." (PMID 38633941, 2024). "We concluded that the patient presented a metastatic abdominal paraganglioma associated with an SDHB mutation and we reinforced the need to perform genetic screening for all adrenal/extra-adrenal lesions characteristic of PHEO/PGL." (PMID 39129823, 2024). "Testing for the germline SDHB mutation in patients with paraganglioma is recommended by Clinical Practice Guidelines." (PMID 38667494, 2024). "SDHB pathogenic variant, positive family history of paraganglioma, younger age at presentation, functional secretory tumors, and rapidly increasing size are factors associated with a higher risk of metastasis." (PMID 38672548, 2024). "A recent review reported that 66% of SDHB mutation carriers had thoraco-abdominal paragangliomas, 25% had head and neck paragangliomas, 12% had pheochromocytomas, 14% had RCC, and 2% had gastrointestinal stromal tumors (GISTs)." (PMID 39201746, 2024). "SDHB mutation is the underlying cause of paraganglioma development in 50–97% of the cases resulting from decreased SDH production, consequent carotid body hypoxia, hyperplasia, and tumor development." (PMID 38664798, 2024). "At least a third of patients with pheochromocytomas and paragangliomas have disease-causing germline mutation, and mutations in the succinate dehydrogenase complex sulfur subunit B (SDHB) gene lead to metastatic disease in at least 40% of affected individuals." (PMID 39677999, 2024).
paraganglioma (continued). "We concluded that the patient presented a metastatic abdominal paraganglioma associated with an SDHB mutation." (PMID 39129823, 2024). "SDHA and SDHB germline pathogenic variants are associated with pheochromocytomas and paragangliomas, but SDHB ones have an increased risk of metastatic disease, which lead to a higher morbidity and mortality rate." (PMID 39194755, 2024). "In 2001, the SDHB gene encoding the iron–sulfur catalytic subunit of succinate dehydrogenase, located on chromosome 1q35–36.1, was also associated with paraganglioma." (PMID 39649680, 2024). "Extra-adrenal paragangliomas are associated with a higher incidence of cancer metastasis more commonly associated with SDHB mutation." (PMID 38473309, 2024). "The most commonly used terms for the “Etiology study” cluster were paraganglioma, germline mutation, genetics and succinate dehydrogenase subunit B(SDHB)." (PMID 37680890, 2023). "A missense variant in SDHB (NM_003000.3:c.642G>C, p.Gln214His) was detected by targeted panel sequencing of pheochromocytoma/paraganglioma-related genes." (PMID 37900184, 2023). "Pheochromocytomas and paragangliomas (PPGLs) with pathogenic mutations in the succinate dehydrogenase subunit B (SDHB) are associated with a high metastatic risk." (PMID 36946182, 2023). "Histological review confirmed a diagnosis of a metastatic SDHB-deficient paraganglioma with nodal involvement." (PMID 36440187, 2022). "Familial paraganglioma syndromes are a group of inherited cancer syndromes characterized by the presence of paragangliomas (including pheochromocytoma), and the loss of SDHB immunoreactivity has a high predictive value for SDHB, SDHC, or SDHD mutations." (PMID 35969220, 2022). "At least 10 per cent of paragangliomas are thought to be malignant and the risk of malignancy is highest in those that carry the succinate dehydrogenase B (SDHB) gene mutation." (PMID 35754193, 2022). "RET and VHL are HSP90 clients, and it has been reported that the expression of HIF-1α and HIF-2α (an HSP90 client) were implicated in the pathogenesis of paraganglioma with SDHB and SDHD mutations." (PMID 35932386, 2022). "CSS, also referred to as the Carney–Stratakis dyad, is a rare inherited predisposition syndrome caused by germline mutations in the SDHB/C or D subunits, which presents with the dyad of GISTs and paragangliomas." (PMID 36358751, 2022). "The cluster analysis showed that SDH-deficient GISTs and SDHB-mutant pheochromocytoma/paraganglioma shared the expression of hypoxia genes that is particularly evident for FOXO3, VLDLR, and ENO2." (PMID 33806389, 2021). "Although his family history was negative, genetic testing for known germline mutations was positive for SDHB mutation, confirming the diagnosis of hereditary paraganglioma/pheochromocytoma syndrome type 4 (PGL4)." (PMID 33575936, 2021). "Risk factors for recurrence of pheochromocytoma and paraganglioma differ, with primary tumor size and average Ki-67 count representing independent predictors for pheochromocytoma patients and SDHB mutations predicting paraganglioma recurrence." (PMID 34899602, 2021). "In our opinion, the main metastasis predictors for paragangliomas of all localizations are as follows: germline mutation in the SDHB gene, high Ki-67 index, and high plasma level of 3-methoxytyramine." (PMID 34833055, 2021). "Sporadic and familial mutations in SDHB result in paragangliomas and pheochromocytoma, and support a link between mitochondrial dysfunction and tumorigenesis." (PMID 34863158, 2021). "This cohort was enriched for patients with paragangliomas of the carotid body or cervical sympathetic chain and those with SDHB genetic mutations." (PMID 34277980, 2021). "Patients with mutations in the β-subunit of the succinate dehydrogenase (SDHB) have the highest risk to develop incurable malignant phaeochromocytomas and paragangliomas (PPGLs)." (PMID 34680273, 2021).
paraganglioma (continued). "Three patients had sporadic pheochromocytoma and one patient a SDHB mutation with bone metastases of extra-adrenal abdominal paraganglioma." (PMID 33575936, 2021). "Four patients were found to carry pathogenic SDHB variants, and all four presented with extra-adrenal thoraco-abdominal paragangliomas, including 3 of the 4 patients with urogenital tract involvement." (PMID 33308260, 2020). "Variations in SDHB have been associated with paraganglioma and pheochromocytoma; one patient with paraganglioma had a CH variant in this gene." (PMID 32508881, 2020). "Succinate dehydrogenase subunit B (SDHB) deficiency frequently occurs in cluster I pheochromocytomas and paragangliomas (PCPGs)." (PMID 31979226, 2020). "Variant rs2746462 (SDHB) is related to paraganglioma and gastric stromal cell sarcoma, as well as the hereditary cancer-predisposing syndrome." (PMID 32708070, 2020). "This was attributed to the decreased expression of the DNA repair enzyme O6-methylguanine-DNA methyltransferase (MGMT) consequent to its promoter hypermethylation, as detected in patient SDHB-mutated paraganglioma and pheochromocytoma metastasis." (PMID 32575796, 2020). "This CIIlow complex, detected in patients with SDHB-mutated paragangliomas, was linked to poor survival." (PMID 32575796, 2020). "Germline variants in SDHC are more rarely associated with the development of paragangliomas/pheochromocytomas than variants in SDHB or SDHD." (PMID 30871634, 2019). "Another study, investigating the sensitivity of functional imaging in detecting metastases in patients with SDHB-associated paraganglioma demonstrated an 18F-FDG PET/CT sensitivity approaching 100%." (PMID 30456751, 2018). "Patients with pheochromocytomas larger than 6 cm or paragangliomas of any size and/or those who are carriers of SDHB mutations need imaging studies to localize metastatic disease." (PMID 30540124, 2018). "This can explain why IDH1/2 mutated glioblastomas and SDHB mutated paraganglioma and pheochoromocytoma are more sensitive to TMZ regiments and are associated with better prognoses." (PMID 29342092, 2018). "Patients who are young and those with larger tumors (>6 cm), positive genetic testing (especially SDHB) or paragangliomas have an increased risk of metastasis and require long-term follow-up." (PMID 30540124, 2018). "Mutations in SDHB or SDHD were identified in 10 out of 10 patients with mediastinal paragangliomas, a rare location for paraganglioma development (2%)." (PMID 30456751, 2018). "The most frequent germline mutations in pheochromocytoma and paraganglioma are in the SDHB (10.3%) and SDHD (8.9%) genes." (PMID 30456751, 2018). "In paragangliomas, SDHB alterations were linked to malignancy and SDHD alterations are more frequent in head-and-neck localized tumours." (PMID 28662141, 2017). "We present the first case of pituitary carcinoma occurring in a patient with a succinate dehydrogenase subunit B (SDHB) mutation and history of paraganglioma." (PMID 28284009, 2017). "We have focused on SDHB mutations since of all SDHx mutations the prevalence for this mutation is high in paragangliomas and since it predisposes to malignancy." (PMID 29163802, 2017). "Two patients with NET had mutations in MEN1 gene, one patient with pheochromocytoma had a pathogenic VHL mutation in exon 3, and one patient with paraganglioma had a variant of uncertain significance in SDHB c.287-3C>G." (PMID 29262620, 2017). "One patient with an SDHB mutation had an 11.3 × 7.6 × 9.3 cm pelvic paraganglioma with extensive metastases that remained biochemically negative on repeated testing." (PMID 28476870, 2017). "The pathogenicity of SDHB Ser163Pro according to ClinVar is controversial, but this allele has previously been detected in familial cases of pheochromocytoma and paraganglioma." (PMID 28634180, 2017). "In conclusion, we have documented the first pituitary carcinoma in a patient with a germline mutation of the SDHB gene and paraganglioma." (PMID 28284009, 2017).
paraganglioma (continued). "In metastatic pheochromocytomas and paragangliomas, mutations in the SDHB subunit are associated with activation of SNAIL and SLUG as a result of epigenetic remodeling due to hypermethylation of promoter CpG islands." (PMID 29250487, 2017). "Mutations in SDHB in paragangliomas/pheochromocytomas are associated with the highest mortality rate as well as with a high incidence of malignant tumors and their metastasis." (PMID 28187001, 2017). "The paraganglioma–pheochromocytoma syndromes (SDHx) comprise familial gene mutations, of which the SDHB gene mutation carries a high rate of malignancy." (PMID 28752085, 2017). "Despite the lower penetrance rates in carriers of SDHB mutations compared to mutations in other paraganglioma susceptibility genes, the aggressive behavior of SDHB-linked disease warrants intensive surveillance to identify and resect tumors early." (PMID 27896548, 2017). "At the expression level, most studies utilized immunohistochemistry to measure SDHA and SDHB protein, and showed loss of SDHB in pheochromocytoma–paraganglioma tumors." (PMID 25694510, 2015). "Metastatic pheochromocytomas and paragangliomas (PPGL) are malignant neuroendocrine tumors frequently associated with germline mutations in the SDHB gene." (PMID 26460615, 2015). "Succinate dehydrogenase subunit B (SDHB) mutations are associated with aggressive pheochromocytoma (PHEO)/paraganglioma (PGL) behavior, often resulting in metastatic disease and fatal outcomes." (PMID 25048685, 2014). "It has also been reported that incidence and prevalence of malignant paragangliomas are higher in patients with SDHB mutation." (PMID 23424694, 2013). "Immunohistochemical loss of the succinate dehydrogenase subunit B (SDHB) has recently been reported as a surrogate biomarker of malignancy in sporadic and familial pheocromocytomas and paragangliomas through the activation of hypoxia pathways." (PMID 24213468, 2012). "Added to that, germline mutations in the mitochondrial succinate dehydrogenase (complex II of the oxidative phosphorylation chain) subunits SDHD, SDHC, and SDHB are a frequent cause of paragangliomas of the head and neck and of phaeochromocytomas." (PMID 21541025, 2011). "In particular, patients with SDHB mutations are at higher risk for developing malignant paragangliomas." (PMID 20205783, 2010). "Pheochromocytomas and paragangliomas frequently exhibit mutations in the succinate dehydrogenase (SDH) subunits SDHB, SDHC, SDHD indicating that these SDH subunits act as tumor suppressors in neuroendocrine tissues." (PMID 20398431, 2010). "Subsequently, two other subunits of SDH, SDHC (chromosome 1q21), and SDHB (chromosome 1p36) were implicated in paragangliomas." (PMID 19956719, 2009). "In contrast to paraganglioma in SDHB and SDHC-linked families, both located on chromosome 1, in SDHD-linked families and in the recently described SDH5 (SDHAF2) family, only a mutation inherited via the paternal line results in tumorigenesis." (PMID 19956719, 2009). "In contrast, germline mutations of SDHB were found in all cases of familial pheochromocytoma and/or paraganglioma." (PMID 16405730, 2006). "In conclusion, these data indicate that germline mutations of SDHB and SDHC play a minor role in sporadic head and neck paraganglioma and further underline the importance of germline SDHB mutations in cases of familial pheochromocytoma-paraganglioma." (PMID 16405730, 2006). "The five novel SDHB mutations described here further underline the importance of germline mutations of this gene in cases of paraganglioma and pheochromocytoma." (PMID 16405730, 2006). "Of interest, in a recent study, immunohistochemistry of head and neck paragangliomas with SDHB and SDHD mutations revealed similar suppression of SDHB, which was accompanied by morphologically abnormal mitochondria." (PMID 16103922, 2005).